PACSIN1 (protein kinase C and casein kinase substrate in neurons 1)
Diseases named in the same sentence as PACSIN1 in open-access papers:
PACSIN1 is named in the same sentence as 31 diseases in open-access papers, as found by Europe PMC text mining. Sharing a sentence is not in itself a finding about the gene and the disease. The quoted sentences say what the papers report.
schizophrenia (6 papers, 2019 to 2025). A major psychotic disorder characterized by abnormalities in the perception or expression of reality. "The homolog of NUDT3 in Drosophila, Aps, is involved in insulin signaling, while defects in PACSIN1 have been associated with schizophrenia-like behavior in mice, another condition linked to obesity." (PMID 37620670, 2023). "The importance of PACSINs in human diseases is suggested by genetic studies that revealed, for example, an association between PACSIN1 locus and schizophrenia." (PMID 34990060, 2022). "An association between schizophrenia and a loci near PACSIN1 gene was found in several genetic studies, supporting a potential role for PACSIN1 in the development of schizophrenia." (PMID 34990060, 2022). "These defects, identified in vitro, likely result in the schizophrenia‐like behavior of PACSIN1 deficient mice." (PMID 34990060, 2022). "Several genes showing enhanced THC sensitivity across development, notably pyramidal-enriched Pacsin1, as well as Clu and Snap25, are also implicated in psychiatric diseases such as schizophrenia and mood disorders." (PMID 30283037, 2019). "Several genetic studies suggest a role for PACSIN1 in the development of schizophrenia, which is also supported by the phenotype of mice depleted of PACSIN1." (PMID 34990060, 2022). "Specifically, PACSIN1 knockout mice displayed hyperactivity, reduced anxiety and reduced social interaction, all typical schizophrenia‐like behaviours in mice." (PMID 34990060, 2022). "In 2008, Pennington and co‐workers found that PACSIN1 protein expression is reduced in the dorsolateral prefrontal cortex in patients with schizophrenia." (PMID 34990060, 2022). "Improper expression of PACSIN1 can lead to neurological diseases such as Huntington’s disease and schizophrenia." (PMID 34422904, 2021). "In addition, mice lacking PACSIN1 displayed more interest in new objects placed in the cage, similar to mice used as models for schizophrenia." (PMID 34990060, 2022).
gastric cancer (3 papers, 2024 to 2025). A primary or metastatic malignant neoplasm involving the stomach. "Deficiency of PACSIN1 enhances chemosensitivity of gastric cancer to ICB therapy and enhances antigen presentation." (PMID 40714319, 2025). "PACSIN1, an oncogene overexpressed in gastric cancer, especially in immunologically cold tumours, suppresses antitumour immunity by promoting lysosomal fusion and selective autophagy of MHC‐I." (PMID 40673641, 2025). "Gastric cancer (GC) is a common gastrointestinal system malignancy.PACSIN1 functions as an oncogene in various cancers." (PMID 38826133, 2024). "To further determine the roles of PACSIN1 in the antitumor T-cell immunity of GC, we generatedPACSIN1‒/‒ cells using AGS and MKN-45 cells and determined the expression of MHC-I in gastric cancer." (PMID 38826133, 2024).
glioma (3 papers, 2008 to 2023). A benign or malignant brain and spinal cord tumor that arises from glial cells (astrocytes, oligodendrocytes, ependymal cells). "First, we investigated the relationship between PACSIN1 and clinical indicators of gliomas (grades, IDH1 mutation status, 1p/19q codeletion status and different molecular subtypes defined by TCGA network)." (PMID 34422904, 2021). "The PACSIN1 expression is negatively correlated with the malignant degree of gliomas and positively associated with the OS, indicating that PACSIN1 would play an essential role in the occurrence and development of gliomas and might be a potential new biomarker and targeted therapy site for gliomas." (PMID 34422904, 2021). "PACSIN1 expression is positively correlated with OS in all gliomas and it was found that PACSIN1 influenced the occurrence and development of gliomas through synaptic transmission." (PMID 34422904, 2021). "The expression of PACSIN1 is lower in gliomas compared with normal group by analyzing CGGA and GSE4290 datasets." (PMID 34422904, 2021). "In order to further explore the relationship between PACSIN1 and gliomas, we retrospectively analyzed a total of 1,546 glioma patients from CGGA, TCGA, GSE16011, GSE58218 datasets and 15 glioma samples." (PMID 34422904, 2021). "To further verify this finding, we performed the receiver operating characteristic curve (ROC) to verify the relationship between PACSIN1 expression and gliomas at all grades of the mesenchymal molecular subtype." (PMID 34422904, 2021). "In order to explore the impact of PACSIN1 on the survival of glioma patients, we analyzed the PACSIN1 expression in the survival status and survival time of 325 samples from the CGGA dataset and 603 samples from the TCGA dataset." (PMID 34422904, 2021). "In order to explore the PACSIN1 expression in gliomas further, we analyzed the PACSIN1 expression in different molecular subtypes (Classical, Mesenchymal, Neural, and Proneural) defined by the TCGA network." (PMID 34422904, 2021). "In this study, we conducted functional annotation and pathway analysis of the DEGs of PACSIN1, and found that PACSIN1 affects the occurrence and development of gliomas mainly through synaptic transmission." (PMID 34422904, 2021). "This study provides a basis for the following clinical studies on PACSIN1 in gliomas, and offers new ideas for targeted therapy of gliomas." (PMID 34422904, 2021). "The results showed that the mRNA expression of PACSIN1 was negatively correlated with glioma grades (p < 0.0001) and was significantly lower in the grade IV group." (PMID 34422904, 2021). "When observing the survival time of each group in the CGGA dataset, the results explained that the patients with low expression of PACSIN1 significantly shortened OS in all grades of gliomas (p < 0.0001)." (PMID 34422904, 2021). "After data collation, Kruskal-Wallis rank sum test was conducted to detect the expression difference of PACSIN1 among patients with different glioma grades." (PMID 34422904, 2021). "In order to further verify the correlation between PACSIN1 and glioma grades, we collected pathological tissue samples from 15 patients in different grades." (PMID 34422904, 2021). "The study aims to explore PACSIN1 as a prognostic factor that can predict overall survival (OS) for gliomas." (PMID 34422904, 2021). "In the DEGs screening of CGGA and GSE4290 datasets between the tumour group and the normal group, we obtained the gene PACSIN1 and found that it significantly downregulated in gliomas." (PMID 34422904, 2021). "IHC results was consistent with database results that PACSIN1 protein expression was negatively correlated with glioma grades and there was statistical significance among each grade (p < 0.0001)." (PMID 34422904, 2021).
glioma (continued). "Finally, in order to explore the mechanism of PACSIN1 inhibiting the occurrence and development of gliomas, total 224 DEGs were screened out through correlation analysis, and functional annotation and pathway analysis were conducted." (PMID 34422904, 2021). "The results indicated that PACSIN1 plays a vital role in the progression of gliomas." (PMID 34422904, 2021). "Finally, it was found that PACSIN1 mainly affects the occurrence and development of gliomas through synaptic transmission." (PMID 34422904, 2021). "Finally, we preliminarily explored the possible mechanism by which PACSIN1 inhibits the progression of gliomas." (PMID 34422904, 2021). "The higher the glioma grade, the lower the PACSIN1 protein expression." (PMID 34422904, 2021). "In this study, PACSIN1 was combined with gliomas for the first time." (PMID 34422904, 2021). "The results indicated that PACSIN1 may regulate synaptic transmission to affect the occurrence and development of gliomas." (PMID 34422904, 2021). "The PACSIN1 expression in glioma grades was extracted from CGGA mRNAseq_325 samples." (PMID 34422904, 2021). "Univariate and multivariate analyses verified that PACSIN1 could be an independent prognostic factor, which has a certain predictive effect on the occurrence and development of glioma patients." (PMID 34422904, 2021). "It makes us curious whether these genes play a certain regulatory role in the influence of PACSIN1 on the occurrence and development of gliomas, which is also our direction for further exploration and verification in the future." (PMID 34422904, 2021). "If the PACSIN1 expression can be interfered in the body, so as to regulate the synaptic transmission pathway, it will make an outstanding contribution to the inhibition of the occurrence and development of gliomas, which is of great significance for glioma patients." (PMID 34422904, 2021). "Besides, PACSIN1 also downregulated in the mesenchymal molecular subtype group, suggesting that PACSIN1 would be a biomarker of the mesenchymal molecular subtype gliomas, with a more malignant phenotype and a worse prognosis." (PMID 34422904, 2021). "Therefore, we hypothesized that PACSIN1 expression is related to the occurrence and development of gliomas." (PMID 34422904, 2021). "Univariate regression analysis results showed that PACSIN1 (p < 0.0001), with all clinical indicators including age (p < 0.0001), IDH1 mutation status (p < 0.0001), 1P/19q codeletion status (p < 0.0001), and grade (p < 0.0001) could be used as a predictor of OS of gliomas at all grades." (PMID 34422904, 2021). "The results revealed that PACSIN1 had low expression levels in grade IV, IDH1 wild-type and 1p/19q non-codel group gliomas, and PACSIN1 was considered a mesenchymal molecular subtype marker." (PMID 34422904, 2021). "It still needs our further research and exploration whether PACSIN1 could affect synaptic transmission by modulating AMPA receptors and NMDA receptors, and then influence the occurrence and development of gliomas." (PMID 34422904, 2021).
brain glioma (2 papers, 2021 to 2024). A malignant glioma that involves the brain. "A low level of PACSIN1 in brain glioma patients predicts advanced disease stage and unsatisfactory long-term overall survival, suggesting thatPACSIN1 may act as an antitumor gene in brain glioma." (PMID 38826133, 2024).
breast carcinoma (2 papers, 2018 to 2024). "For instance, overexpressed PACSIN1 is associated with poor overall survival in luminal breast cancer patients." (PMID 38826133, 2024). "For instance, overexpression of PACSIN1 in luminal breast cancer predicts poor prognosis and promotes the aggressiveness of breast cancer cells, suggesting thatPACSIN1 may function as an oncogene in luminal breast cancer." (PMID 38826133, 2024). "Further functional studies on the signature genes are needed to gain a deeper insight into the roles they play in breast cancer onset, with specific emphasis on PACSIN1 because its direct involvement in cancer has not yet been reported." (PMID 29642861, 2018).
Huntington disease (2 papers, 2021 to 2022). Huntington disease (HD) is a rare neurodegenerative disorder of the central nervous system characterized by unwanted choreatic movements, behavioral and psychiatric disturbances and dementia. "Supporting their hypothesis, immunostaining of presymptomatic patients with Huntington's disease indicate a relocation of PACSIN1 to the perinuclear area in neurons of the frontal cortex." (PMID 34990060, 2022). "PACSIN1, but not PACSIN2 or PACSIN3, has also been shown to interact with huntingtin, a protein involved in Huntington's disease." (PMID 34990060, 2022).
Obesity (2 papers, 2019 to 2023). Accumulation of substantial excess body fat. "NUDT3, SPDEF, and PACSIN1 have been identified in a closely linked region that is associated with obesity or carcass traits, such as body growth and size, in human or pigs." (PMID 31188900, 2019).
ADNP syndrome (1 paper, 2019). "One such area occurs in PACSIN1, which showed hypomethylation in all ADNP syndrome samples and has a considerable overlap in cellular function with ADNP." (PMID 31029150, 2019).
autism (1 paper, 2025). Persistent deficits in social interaction and communication and interaction as well as a markedly restricted repertoire of activity and interest as well as repetitive patterns of behavior. "Genes reported as potential blood biomarkers of mental health, such as PACSIN1 and SPTBN1 (associated with addiction-related behavior), GPR19 (associated with depression), and AUTS2 (associated with autism), were highlighted in the STRING analysis of this study." (PMID 40917096, 2025).
cognitive decline (1 paper, 2021). "Overlapping the proteins consistent in both AD datasets with data from transgenic mice revealed four novel, high-confidence candidates that were associated with cognitive decline and drug-mediated multi-target kinase inhibition: PACSIN1, GJA1, VSNL1 and NDUFB5." (PMID 33530349, 2021).
dementia (1 paper, 2022). Loss of intellectual abilities interfering with an individual's social and occupational functions. "These loci are associated with several dementia-related genes, including PON1, AP2A2, MAGI2, POT1, ITGAX, PACSIN1, SLC2A8, and EIF4E." (PMID 35299244, 2022).
idiopathic pulmonary fibrosis (1 paper, 2022). Idiopathic pulmonary fibrosis (IPF) is a nonneoplastic pulmonary disease that is characterized by the formation of scar tissue within the lungs in the absence of any known cause. "PACSIN1 mRNA was found to be differentially expressed in a study aiming to find novel biomarkers for idiopathic pulmonary fibrosis." (PMID 34990060, 2022). "Specifically, the expression of PACSIN1 was lower in the circulation of patients with severe compared to mild idiopathic pulmonary fibrosis." (PMID 34990060, 2022).
lymph node metastasis (1 paper, 2024). "Moreover, high expression of PACSIN1 was associated with advanced stages, lymph node metastasis and poor prognosis." (PMID 38826133, 2024).
melanoma (1 paper, 2013). A malignant, usually aggressive tumor composed of atypical, neoplastic melanocytes. "Introduction of a melanoma-associated mutation, P52L, into this peptide reduces pseudosubstrate autoinhibition of PAK6, and increases phosphorylation of its substrate PACSIN1 (Syndapin I) in cells." (PMID 24204982, 2013). "We find that PACSIN1 shows significantly increased phosphorylation when co-transfected with the P52L mutant compared to the wild-type PAK6, suggesting that the melanoma-associated mutation indeed functions to increase kinase activity." (PMID 24204982, 2013).
pulmonary fibrosis (1 paper, 2022). Chronic progressive interstitial lung disorder characterized by the replacement of the lung tissue by connective tissue, leading to progressive dyspnea, respiratory failure, or right heart failure. "However, similar to the potential role of PACSIN1 in cancer onset and progression, the role for PACSIN1 in the development of pulmonary fibrosis remains to be confirmed by further studies." (PMID 34990060, 2022).
tumours (5 papers, 2013 to 2025). "PACSIN1 deficiency enhances antigen presentation, increases CD8+ T cell infiltration, and improves response to ICB, thereby inhibiting tumour growth and liver metastasis." (PMID 40673641, 2025). "As shown inFigure 5A,PACSIN1 knockout or anti-PD1 therapy significantly inhibited GC tumor size and weight." (PMID 38826133, 2024). "Moreover, PACSIN1 deficiency inhibits the lysosomal fusion and selective autophagy of MHC-I, increases CD8+ T-cell infiltration, and suppresses tumor growth and liver metastasisin vivo." (PMID 38826133, 2024). "As shown inFigure 1B,PACSIN1 mRNA expression was significantly increased in tumor tissues." (PMID 38826133, 2024). "This study aimed to investigate the role of PACSIN1 in the tumor microenvironment in GC." (PMID 38826133, 2024). "In this study,PACSIN1 deficiency inhibited lysosomal fusion and selective autophagy of MHC-I and promoted antigen presentation and infiltration of CD8+ T cells, which suppressed tumor growth and liver metastasis and enhanced the chemosensitivity of GC to anti-PD1 therapyin vivo." (PMID 38826133, 2024). "We also analyzed the tumor microenvironment (TME) afterPACSIN1‒/‒ and/or anti-PD-1 antibody injection.PACSIN1 knockout significantly enhanced the effects of anti-PD1 therapy." (PMID 38826133, 2024). "The results from the IHC assay showed that the expression of PACSIN1 in tumor tissues was significantly greater than that in normal tissues." (PMID 38826133, 2024). "In addition, except for PACSIN1 (P > 0.05), the expression levels of FAM107A (P < 0.05) and PTGDS (P < 0.05) were significantly different between tumour and normal samples." (PMID 37325056, 2023). "Accordingly,PACSIN1 knockout-mediated inhibition of GC cell growth was restored inBatf3‒/‒ mice, suggesting that blocking the interaction between MHC-I and PACSIN1 may enhance the tumor cell recognition of CD8+ T cells." (PMID 38826133, 2024). "PACSIN1 knockout markedly decreased tumor size and weight and increased the expression of MHC-I but did not obviously change PD-1 expression.PACSIN1 knockout also increased the infiltration level of CD8+ T cells." (PMID 38826133, 2024).
cancer (4 papers, 2018 to 2024). A tumor composed of atypical neoplastic, often pleomorphic cells that invade other tissues. "Phosphorylation of PACSIN1 at serine 358 also regulates the function of rac1, well established as a regulator of the actin cytoskeleton that is associated with various diseases, such as developmental disorders and cancer." (PMID 34990060, 2022). "PACSIN1 is frequently found to be abnormally expressed in multiple types of cancers." (PMID 38826133, 2024). "However, reports on the roles of PACSIN1 in cancers are contradictory." (PMID 38826133, 2024). "Moreover, PACSIN1 is overexpressed in multiple types of cancers." (PMID 38826133, 2024). "Therefore, the roles of PACSIN1 may vary with the type of cancer." (PMID 38826133, 2024).
neurological diseases (2 papers, 2021 to 2022). "The studies also suggest a role for PACSIN1 in various other neurological disorders but these will require further investigations for detailing the relevance in vivo." (PMID 34990060, 2022).
psychiatric diseases (2 papers, 2019 to 2025). "The overlapped PTSD DEPs include downregulated GABAergic genes SLC32A1, NEGR1, and PACSIN1, which we consider are high-confidence PTSD DEPs, especially NEGR1 which is also a risk gene for multiple psychiatric disorders including MDD and SCZ." (PMID 40301990, 2025).
metabolic disorders (1 paper, 2025). "These additional putative mono/oligogenic SLE genes are involved in type I IFN regulation (DDX58, NLRC4 and PACSIN1), disruption of B cell and T cell tolerance (DOCK8, FAS and LRBA) and metabolic disorders (CYBB, MAN2B1, SLC7A7)." (PMID 40386946, 2025).
neurodegenerative disease (1 paper, 2022). A disorder of the central nervous system characterized by gradual and progressive loss of neural tissue and neurologic function. "It is worth investigating if such proteins sequester PACSIN1 in vivo and reduce its function, thereby potentially impairing basal autophagy and contributing to neurodegenerative disease." (PMID 35771772, 2022).
PACSIN1 also shares sentences with these, for which no sentence is quoted: ciliopathy (1 paper); depression (1); inflammatory bowel disease (1); mood disorder (1); neuropathy (1); osteosarcoma (1); prostate carcinoma (1); prostate tumors (1); pulmonary diseases (1); startle disease (1).